SLC13A5 (solute carrier family 13 member 5)
Diseases named in the same sentence as SLC13A5 in open-access papers (continued):
Sharing a sentence is not in itself a finding about the gene and the disease.
cyst (1 paper, 2017). A sac-like closed membranous structure that may be empty or contain fluid or amorphous material. "In some of the Slc13a5-/- mice the enamel organ epithelium formed a few small cyst-like structures with clear to granular eosinophilic contents (not shown)." (PMID 28406943, 2017).
dentinogenesis imperfecta (1 paper, 2021). Dentinogenesis imperfecta (DGI) is a hereditary dentin defect characterized by abnormal dentin structure resulting in abnormal tooth development. "Interestingly, the Slc13a5 deficient mouse has some phenotypic overlap with OI, as it shows amelogenesis imperfecta, a tooth enamel defect resembling dentinogenesis imperfecta as well as low bone mineral density." (PMID 34069814, 2021).
Dravet syndrome (1 paper, 2024). "Out of the 12 studies, 10 included patients with Dravet syndrome, one included patients with Dravet syndrome and other DEEs,43 and one study (a case series) included patients with SLC13A5‐related DEEs38." (PMID 39360600, 2024).
early-onset epilepsy (1 paper, 2022). "In children SLC13A5-related early-onset epilepsy, which usually occurs within the first few weeks after birth, seizures continue as the children grow." (PMID 36923948, 2022).
osteogenesis imperfecta (1 paper, 2023). Osteogenesis imperfecta (OI) comprises a heterogeneous group of genetic disorders characterized by increased bone fragility, low bone mass, and susceptibility to bone fractures with variable severity. "Another mouse model of bone disease, osteogenesis imperfecta (OI), showed 2.5-fold increased SLC13A5 expression levels in bone and abnormal mineralization and may provide another hint for beneficial effects of SLC13A5 inhibition on bone health." (PMID 38132868, 2023).
pancreatic cancer (1 paper, 2014). "The panel of promoter CGIs in this study included KIRREL2 and SLC13A5, which have previously been identified as the differentially-methylated CGIs in pancreatic cancer and cloned using methylated CpG island amplification-representational difference analysis from pancreatic cancer cell lines." (PMID 25289081, 2014).
renal carcinoma (1 paper, 2021). A carcinoma arising from the epithelium of the renal parenchyma or the renal pelvis. "Similar results were also observed in renal cancer cells where DNA hypermethylation on the CpG islands of the SLC13A5 gene was identified in a cluster of renal cancer patients with poor survival rates." (PMID 34677420, 2021).
renal cell carcinoma (1 paper, 2014). "For example, SLC13A5, a member of the solute carrier (SLC) families and a Na+/sulfate/selenate/thiosulfate/carboxylate symporter, is one of the hallmarks of CIMP in renal cell carcinoma." (PMID 25289081, 2014).
sleep abnormalities (1 paper, 2024). "Screening for sleep disturbances and treatment may help improve quality of life for SLC13A5 Citrate Transporter Disorder patients." (PMID 39457462, 2024). "While sleep disorders are common in children with neurodevelopmental disorders, sleep abnormalities have not been reported in SLC13A5 patients." (PMID 39457462, 2024).
status epilepticus (1 paper, 2021). Status epilepticus is defined as a continuous seizure lasting more than 30 min, or two or more seizures without full recovery of consciousness between any of them. "A high rate of status epilepticus is reported with SLC13A5 pathogenic variants." (PMID 33919646, 2021). "SLC13A5 (solute carrier, family 13, member 5): Patients present a consistent phenotype: neonatal-onset EOEE with clonic and/or subtle seizures and a high rate of status epilepticus." (PMID 33919646, 2021).
tooth hypoplasia (1 paper, 2017). "The role of NaCT in the formation of mineralized organs was implicated in human genetics studies, showing that SLC13A5 mutations with loss of function were associated with tooth hypoplasia, hypodontia, and gingival hyperplasia." (PMID 28406943, 2017).
metabolic disorders (10 papers, 2015 to 2025). "SLC13A5 is a single-gene cause of a severe metabolic disorder that has received increasing attention in recent years." (PMID 36984771, 2023). "Accumulating evidence has revealed that SLC13A5 plays an important role in controlling the hepatic citrate level and is linked to various metabolic disorders." (PMID 34677420, 2021). "SLC13A5 has been proposed as a promising therapeutic target for the treatment of these metabolic disorders." (PMID 34677420, 2021). "Inhibition of hepatic extracellular citrate uptake, by blocking the sodium-coupled citrate transporter (NaCT or SLC13A5), has been suggested as a potential therapeutic approach to treat metabolic disorders." (PMID 26620127, 2015).
cancer (9 papers, 2018 to 2025). A tumor composed of atypical neoplastic, often pleomorphic cells that invade other tissues. "After this pair-wise comparison, we did not retrieve genes previously associated with GB, except for SLC13A5, which can show perturbed gene expression and methylation patterns in this cancer type." (PMID 34293049, 2021). "SLC13A2 and SLC13A5 are also upregulated supporting an enhanced import of citrate into cancer cells in cluster 2 tumors." (PMID 36119118, 2022). "Given that citrate in the cytoplasm is obligatory for fatty acid and cholesterol synthesis and for promotion of cancer cell growth and proliferation, SLC13A5 must have relevance to cancer, at least in the liver where its expression is the most abundant." (PMID 33425906, 2020). "SLC13A5 as another contributor to cytoplasmic citrate detected in cancer cells." (PMID 33425906, 2020). "We have shown recently that cancer cells take up extracellular citrate through the pmCiC, and others have shown a similar role for the Na+-coupled citrate transporter NaCT (SLC13A5)." (PMID 33425906, 2020). "However, extracellular citrate treatment in HCCs with high SLC13A5/NaCT expression had reduced glucose uptake due to HIF1α degradation, inducing the failure of metabolic adaptation to hypoxia, resulting in anti-cancer effects in in vitro and in vivo animal models." (PMID 35884416, 2022). "However, recent study has revealed that depletion of SLC13A5 or PMCT results in reduction of cell proliferation in HepG2 and Huh7 cancer cells." (PMID 29928578, 2018).
neurological disorder (3 papers, 2021 to 2023). "SLC13A5 citrate transporter disorder is a rare neurological disease caused by pathogenic loss-of-function variants in the SLC13A5 gene." (PMID 37025451, 2023). "SLC13A5 was first associated with a pediatric neurologic disorder in 2014." (PMID 37025451, 2023).
tumor (3 papers, 2021 to 2025). "Inhibitors of SLC13A5 can reduce fat accumulation, enhance insulin sensitivity, and inhibit tumor cell proliferation." (PMID 41425581, 2025). "This provides the molecular basis for tumor-promoting potential of SLC13A5." (PMID 34677384, 2021). "Recent studies have shown that SLC13A5 is a tumor promoter in hepatocellular carcinoma." (PMID 34677384, 2021). "Tumor regions without increased 18F-FDG uptake showed increased SLC13A5 and SLC16A1 expression, whereas tumors with increased 18F-FDG uptake showed high SLC2A1 and HIF1α." (PMID 35884416, 2022).
movement disorder (2 papers, 2022 to 2023). Neurological conditions resulting in abnormal voluntary or involuntary movement, which may impact the speed, fluency, quality and ease of movement. "It helps highlight phenotypic features that will require careful characterization in a natural history study, for example, tone and movement disorder in SLC13A5 citrate transporter disorder, which frequently had conflicting documentation within a single subject on sequential exams." (PMID 37025451, 2023).
brain disorder (1 paper, 2023). A disease affecting the brain or part of the brain. "In the nervous system, SLC13A5 citrate transport disorders are associated with pediatric epilepsy, Kohlschütter–Tönz syndrome, and other brain disorders, leading to imbalanced metabolic homeostasis affecting brain citrate and acetyl-CoA metabolism as well as ionic homeostasis." (PMID 36984771, 2023).
genetic diseases (1 paper, 2024). "IPSC-derived cellular systems are a powerful tool for modeling rare human genetic diseases, such as SLC13A5." (PMID 38392976, 2024).
kidney disease (1 paper, 2023). "SLC13A5 inhibition has been proposed as a target for reducing progression of kidney disease." (PMID 38110950, 2023). "However, no SLC13A5 inhibitor has yet entered clinical study, and so evidence of its efficacy for ameliorating progression of kidney disease in humans is limited." (PMID 38110950, 2023).
SLC13A5 also shares sentences with these, for which no sentence is quoted: developmental and epileptic encephalopathy (4 papers); autism spectrum disorder (2); breast carcinoma (2); chronic kidney disease (2); early infantile epileptic encephalopathy (2); infantile epileptic encephalopathy (2); Kohlschütter-Tönz syndrome (2); Machado-Joseph disease (2); adrenal pheochromocytoma (1); Angelman syndrome (1); attention deficit-hyperactivity disorder (1); autosomal recessive early infantile epileptic encephalopathy (1); bladder cancer (1); cardiovascular diseases (1); Cognitive impairment (1); cone-rod dystrophy (1); developmental disability (1); developmental epileptic encephalopathy-25 (1); Dystonia (1); facial dysmorphism (1); fragile X syndrome (1); GM1 gangliosidosis (1); hyperlipidemia (1); Hypodontia (1); Hypotonia (1); hypotrichosis (1); Kohlschütter-Tonz like syndrome (1); limb girdle muscular dystrophy type 2S (1); Macrocephaly (1); mitochondrial DNA depletion syndrome (1).
A further 10 diseases each share a sentence with SLC13A5 in 1 paper.